GFAP (glial fibrillary acidic protein)
Diseases named in the same sentence as GFAP in open-access papers (continued):
Sharing a sentence is not in itself a finding about the gene and the disease.
inflammation (8 papers, 2011 to 2025). Aberrant reaction of the microcirculation characterized by movement of fluid and leukocytes from the blood into extravascular tissues. "The GFAP antibodies are likely a clinically insignificant bystander in this case and possibly in other diseases with CNS inflammation." (PMID 36737749, 2023). "In the GFAP-IL6 transgenic mouse, IL6 is overexpressed in the brain under the control of the GFAP promoter, as a model of chronic brain inflammation." (PMID 35978857, 2022). "To assess if gliosis and hypothalamic inflammation were present, we analyzed glial fibrillary acidic protein (GFAP), ionized calcium-binding adapter molecule 1 (Iba1) and c-jun N-terminal kinase (JNK) activation." (PMID 32849298, 2020). "Moreover, paraneoplastic or post‐viral autoimmunity has frequently been reported in GFAP‐astrocytopathy, emphasizing the role of T cells as the primary immune cells involved in CNS inflammation." (PMID 40581835, 2025). "We hypothesize that GFAP CSF antibodies may be clinically insignificant bystanders in diseases with marked CNS inflammation." (PMID 36737749, 2023). "However, the number and distribution of GFAP-positive EGCs in the inflamed and non-inflamed gut of IBD patients is controversially discussed and only few data exist on EGCs in the intestines of IBD patients and during gut inflammation." (PMID 21235736, 2011).
neurodevelopmental disorder (7 papers, 2014 to 2024). A behavioral and cognitive disorder with onset during the developmental period that involves impaired or aberrant development of intellectual, motor, or social functions. "The results showed that several DAPs were associated with DCX or GFAP, indicating that acetylation may have a significant impact on neurodevelopmental disorders during CIH." (PMID 38455734, 2024). "GFAP expression is a late benchmark in astrocyte development and maturation and our research outcomes stress that food restriction can lead to a precocious differentiation of astrocytes strengthening the hypothesis of astrocytes as possible drivers of neurodevelopmental disorders." (PMID 33935642, 2021). "Serum levels of Nfl and GFAP have been mostly investigated in some neurological conditions rather than in ASD or other neurodevelopmental disorders." (PMID 36769380, 2023). "Despite some limitations of our GFAP-Coasy mouse model, we were able to clearly link the absence of the Coasy gene in astroglial lineage, to a neurodevelopmental disorder, that had previously only been observed in a Coasy knock-out zebrafish model and in patients with PCH12." (PMID 39301217, 2024).
adenocarcinoma (4 papers, 2011 to 2024). A common cancer characterized by the presence of malignant glandular cells. "The results of some studies have shown the usefulness of the immunohistochemical marker GFAP in the differential diagnosis between PA and PADK, the adenocarcinoma cells being immunonegative for this marker." (PMID 38929710, 2024). "When mutant GFAP was transfected into non-astrocyte SW13vim- cells, an adenocarcinoma cell line lacking vimentin, GFAP aggregates were formed." (PMID 39596168, 2024).
kidney disease (3 papers, 2022 to 2024). "GFAP: Model 7 showed lower average values in men or those who were obese, faster average increases in those Stage 3 kidney disease and with A+ status, higher average values in those with Stages 2 and 3 kidney disease or A+ status." (PMID 38970274, 2024).
bacterial infection (2 papers, 2019 to 2025). "We further found an increase in the immunoreactivity for the microglial marker Iba-1 and a trend in increase of GFAP immunoreactivity (an astrocytic marker) in the hippocampi of infected pups 24 h after bacterial infection when compared to sPBS-injected mice." (PMID 30975983, 2019).
cardiovascular diseases (2 papers, 2021 to 2024). "Also, as all control cases died from sudden cardiovascular diseases, the occurrence of GFAP in neurons might be related to this disorder." (PMID 34114049, 2021).
kidney (2 papers, 2022 to 2023). "This was further confirmed in the kidney IR scenario in the expressions of Iba-1 and GFAP and the increase in cytokines in the hippocampus and cortex at the mRNA level." (PMID 36428560, 2022).
mitochondrial disease (2 papers, 2016 to 2023). "Astrocytes also adopted a reactive phenotype with an upregulation of glial fibrillary acidic protein (GFAP), which is commonly observed in post-mortem brain tissues from patients with mitochondrial disease." (PMID 37298649, 2023).
overlap syndrome (2 papers, 2024 to 2025). "GFAP astrocytopathy can coexist with a variety of antibodies, which is known as overlap syndrome." (PMID 38996095, 2024).
vasculopathy (2 papers, 2022 to 2024). "The vasculopathy in PLX5622-treated GFAP-IL6 and GFAP-IFN mice was comparable to untreated animals." (PMID 36389783, 2022).
GFAP also shares sentences with these, for which no sentence is quoted: concussion (26 papers); brain cancer (13); all (6); colorectal cancer (5); progressive supranuclear palsy (5); Aicardi-Goutières Syndrome (4); cognitive disorder (4); influenza (4); normal pressure hydrocephalus (4); Pick disease (4); alcoholism (3); autism spectrum disorder (3); cavernous angioma (3); lung adenocarcinoma (3); lysosomal storage disease (3); megalencephalic leukoencephalopathy (3); prediabetes (3); rhabdomyosarcoma (3); -traumatic stress disorder (2); adrenoleukodystrophy (2); age-related macular degeneration (2); alcohol abuse (2); cardioembolic stroke (2); Coma (2); corticobasal syndrome (2); follicular dendritic cell sarcoma (2); Hyperinsulinemia (2); idiopathic intracranial hypertension (2); infectious disease (2); Leber hereditary optic neuropathy (2).
A further 198 diseases each share a sentence with GFAP in 2 papers or fewer.